DHX33 (DEAH-box helicase 33)
Description:
Implicated in nucleolar organization, ribosome biogenesis, protein synthesis and cytoplasmic dsRNA sensing (By similarity). Stimulates RNA polymerase I transcription of the 47S precursor rRNA. Associates with ribosomal DNA (rDNA) loci where it is involved in POLR1A recruitment. In the cytoplasm, promotes elongation-competent 80S ribosome assembly at the late stage of mRNA translation initiation. Senses cytosolic dsRNA mediating NLRP3 inflammasome formation in macrophages and type I interferon production in myeloid dendritic cells. Required for NLRP3 activation induced by viral dsRNA and bacterial RNA. In dendritic cells, required for induction of type I interferon production induced by cytoplasmic dsRNA via the activation of MAPK and NF-kappa-B signaling pathways (By similarity).
Synonyms: DDX33; FLJ21972; DKFZp762F2011
Tractability: PROTAC: UniProt records ubiquitination sites on it; ubiquitination databases record sites on it.
Gene: Protein-coding gene on chromosome 17 (5,440,917 to 5,468,982, reverse strand). Ensembl gene ENSG00000005100.
Subcellular location: Nucleus, nucleolus; Nucleus, nucleoplasm; Cytoplasm; Nucleus; Inflammasome
Subcellular location (Human Protein Atlas): Nucleoli
Gene Ontology:
Molecular function: double-stranded RNA binding; mRNA binding; protein binding; rDNA binding; ribosomal large subunit binding; RNA binding; helicase activity; ATP binding; ATP hydrolysis activity; DNA-binding transcription factor binding; nucleic acid binding; RNA helicase activity
Biological process: positive regulation of NLRP3 inflammasome complex assembly; positive regulation of transcription by RNA polymerase I; positive regulation of MAPK cascade; positive regulation of type I interferon production; translational initiation
Cellular component: canonical inflammasome complex; cytoplasm; NLRP3 inflammasome complex; nucleolus; nucleoplasm; nucleus
Genetic constraint (gnomAD): Loss-of-function variants: 40 observed, 70.09 expected, observed/expected ratio (o/e) 0.57, 90% interval 0.44 to 0.74. The upper end of that interval is the gene's LOEUF score, 0.74, which puts it in group 3 of 6, group 1 being the genes least tolerant of losing a copy. Missense variants: 836 observed, 951.04 expected, observed/expected ratio (o/e) 0.88, 90% interval 0.83 to 0.93. Synonymous variants: 358 observed, 381.77 expected, observed/expected ratio (o/e) 0.94, 90% interval 0.86 to 1.02.
Homologues: Orthologues: chimpanzee DHX33 (99% identical), macaque DHX33 (98% identical), rat Dhx33 (93% identical), mouse Dhx33 (93% identical), guinea pig DHX33 (92% identical), pig DHX33 (89% identical), rabbit DHX33 (89% identical), dog DHX33 (89% identical), tropical clawed frog dhx33 (76% identical), zebrafish dhx33 (70% identical), Drosophila melanogaster ath (43% identical), Caenorhabditis elegans let-355 (38% identical). Paralogues in human: DHX8 (43% identical), DHX16 (42% identical), DHX35 (41% identical), DHX38 (40% identical), DHX15 (39% identical), DHX37 (37% identical), DHX34 (32% identical), DHX40 (32% identical), DHX57 (30% identical), YTHDC2 (28% identical), DHX36 (27% identical), DHX29 (27% identical), and 6 more.
Diseases named in the same sentence as DHX33 in open-access papers:
DHX33 is named in the same sentence as 15 diseases in open-access papers, as found by Europe PMC text mining. Sharing a sentence is not in itself a finding about the gene and the disease. The quoted sentences say what the papers report.
glioblastoma (2 papers, 2020 to 2023). The most malignant astrocytic tumor (WHO grade IV). "DHX33 is highly expressed in several cancer types, including glioblastoma." (PMID 32575790, 2020).
hepatocellular carcinoma (2 papers, 2023 to 2024). A malignant tumor that arises from hepatocytes. "MiR-634 has been reported to exhibit antitumor activities toward hepatocellular carcinoma via Rab1A and DHX33." (PMID 38704809, 2024). "The latest research shows HOTAIR knockdown suppressed cell proliferation, migration and invasion, and promoted apoptosis via regulating miR-526b-3p/DHX33 axis in hepatocellular carcinoma (HCC) cells." (PMID 37576402, 2023).
viral infection (2 papers, 2017 to 2024). "Indeed, TRIM33 has been shown to regulate NLRP3 inflammasome activation in response to bacterial or viral infection through a direct interaction with DHX33 in the cytoplasm and to regulate Ifnb1 transcription at the late stages of BMDM activation." (PMID 27974684, 2017). "During viral infections, RNase L has been demonstrated to promote NLRP3 inflammasome activation through a signaling pathway involving DHX33 and MAVS, leading to the production of IL-1B in bone marrow-derived dendritic cells." (PMID 38473966, 2024).
colon cancer (1 paper, 2025). "Previous research has shown that DHX33 is highly expressed in colon cancer tissues and cell lines, while its deficiency resulted in tumor growth retardation in colon cancer cells in an in vivo xenograft model." (PMID 39886381, 2025).
colorectal cancer (1 paper, 2025). A primary or metastatic malignant neoplasm that affects the colon or rectum. "However, the connection between DHX33 expression levels and resistance to standard chemotherapy in colorectal cancer has not been thoroughly investigated, introducing a potentially novel perspective in our findings." (PMID 39886381, 2025).
sarcoma (1 paper, 2023). A usually aggressive malignant neoplasm of the soft tissue or bone. "The association between the differential expression of DHX33 and the prognosis for sarcoma was assessed using survival analysis." (PMID 37115050, 2023). "We then further investigated the association between DHX33 and tumor-infiltrating immune cells in sarcoma using the TIMER database." (PMID 37115050, 2023). "We found that the expression of DHX33 in sarcoma was substantially correlated with 30 immunostimulators and 20 immunoinhibitors." (PMID 37115050, 2023). "More importantly, the relationship between DHX33 and the prognosis of patients with sarcoma remains to be clarified." (PMID 37115050, 2023). "In the present study, we examined the potential value of DHX33 as a prospective target for immunotherapy in sarcoma by evaluating the link between DHX33 and prognosis of patients with sarcoma." (PMID 37115050, 2023). "To investigate the function of DHX33 in the immune microenvironment of sarcoma, we used GSEA analysis to probe into the pertinent signaling pathways in which DHX33 is involved." (PMID 37115050, 2023). "Our study emphasized that DHX33 may be involved in the immune microenvironment of sarcoma and play an important role." (PMID 37115050, 2023). "Subsequently, we also examined the immunomodulatory role of DHX33 in the development of sarcoma." (PMID 37115050, 2023). "As a result, it is possible that DHX33 might serve as an immunotherapeutic target for sarcoma." (PMID 37115050, 2023). "Next, we explored whether the expression level of DHX33 correlated with immune cell in sarcoma." (PMID 37115050, 2023). "However, the relationship between DHX33 and sarcoma remains unknown." (PMID 37115050, 2023).
cancer (11 papers, 2016 to 2025). A tumor composed of atypical neoplastic, often pleomorphic cells that invade other tissues. "A deficiency of DHX33 induced a significant increase of G1-phase cells and a marked decrease of S-phase cells in different cancer cells." (PMID 34207140, 2021). "Recognizing that the DNA-cleaving activity of DHX33 helicase during DNA replication can lead to cancer, Wang and coworkers designed DHX33 small-molecule inhibitors." (PMID 40430417, 2025). "The fact that cancer cells demonstrate heightened sensitivity to DHX33 downregulation, highlights its potential as a promising target for cancer therapy." (PMID 39886381, 2025). "The DHX33 gene, identified in our correlation analysis, plays a pivotal role in cancer cell proliferation and growth." (PMID 39886381, 2025). "We discovered that 263 cancer samples had considerably higher levels of DHX33 expression than did 2 normal samples." (PMID 37115050, 2023). "DEAH-box helicase 33 (DHX33) is an RNA helicase that has been identified to promote the progression of a variety of cancers." (PMID 37115050, 2023). "DHX33 is required for promoting cell cycle progression at the G1-to-S phase transition, which is overexpressed in several types of human cancers, such as lung cancers, hepatocellular carcinoma, lymphoma, colon cancer, and glioblastoma." (PMID 34207140, 2021). "Additionally, DHX33 has been found to stimulate Bcl-2 transcription in many human cancer cell lines." (PMID 39886381, 2025). "Finally, the immune/cancer-related signaling pathways involved in DHX33 were analyzed using gene set enrichment analysis." (PMID 37115050, 2023). "In addition, we thoroughly assessed the connections between DHX33 and infiltrating immune cells, as well as DHX33-mediated immune/cancer signaling pathways." (PMID 37115050, 2023). "Moreover, the knockdown of DDX3 and DHX33 inhibited cell cycle progression by blocking the entry into S phase of cancer cells." (PMID 35723050, 2022). "Thus, DHX33 contributes to the regulation of various aspects of cell proliferation and migration during cancer development." (PMID 33804185, 2021). "DHX33 is a member of the DEAD/DEAH box family of RNA helicases involved in cancer progression." (PMID 32717723, 2020). "MYC binds to DHX33 and promotes PLAU transcription by directly binding to their promoters, thus promoting cancer cell migration." (PMID 35069971, 2022). "From the cross-cancer alteration analysis under the simultaneous query of MYC, NOLC1, DHX33, and CHD7, a large number of cancers possess alterations in these genes." (PMID 27198694, 2016). "For instance, TRIM33 binds to DHX33 and boosts its ubiquitylation at Lys63, resulting in the activation of the NLRP3 inflammasome; TRIM33 targets β‐catenin and mediates its ubiquitylation and degradation to restrain the proliferation of various types of cancer cells." (PMID 34101965, 2021).
tumor (5 papers, 2016 to 2025). "The tumor immune estimation resource analysis revealed a strong correlation between the expression of DHX33 and the abundance of CD8+ T cells and dendritic cells." (PMID 37115050, 2023). "Among the neoantigens are well-known genes associated with tumor progression and metastases, such as HAUS3, NSDHL, MAGEA10, FNDC3B, TEAD1, DHX33, PGM5, and MLL2." (PMID 36607962, 2023). "Furthermore, following the fact that rDNA transcription is greatly influenced by the RAS, MYC, and NPM oncogenes, DHX33 upregulation was shown to be required for enhanced transcription during RAS activation and for RAS-initiated tumor progression." (PMID 27198694, 2016).
DHX33 also shares sentences with these, for which no sentence is quoted: breast carcinoma (1 paper); liver cancer (1); lung adenocarcinoma (1); lung carcinoma (1); lymphoma (1); Obesity (1); retinoblastoma (1).